IL37 (interleukin 37)
Diseases named in the same sentence as IL37 in open-access papers (continued):
Sharing a sentence is not in itself a finding about the gene and the disease.
tonsillitis (1 paper, 2018). Inflammation of the tonsillar tissue. "In unadjusted analysis, patients in the hypertrophy group had stronger tonsillar expression of Tbet (P = 0.03) and IL-37 (P = 0.001) than patients in the recurrent tonsillitis group." (PMID 29942488, 2018). "However, anti-inflammatory immune responses, namely IL-37, might be slightly stronger in patients with tonsillar hypertrophy than with patients with recurrent tonsillitis." (PMID 29942488, 2018).
tumor (86 papers, 2006 to 2026). "Many have reported that IL37 is upregulated by inflammatory stimulus, and hypoxia is known to be linked to the inflammatory state within the tumour environment." (PMID 39500733, 2024). "This study has successfully established a mechanistic connection between two pivotal factors in cancer progression, namely the hypoxic environment and tumour‐associated macrophages (TAMs), through the involvement of IL37 in OSCC." (PMID 39500733, 2024). "The low IL-37 expression in tumor tissues was an independent risk factor for poor prognosis and these primary HCC patients were followed for shorter overall survival (OS) and disease-free survival (DFS)." (PMID 37928545, 2023). "IL-37 levels were found to be correlated with tumor development, stage, nodal metastasis and mutation status, as well as improved survival of patients." (PMID 37298214, 2023). "High IL-37 expression by HCC tumor cells is associated with upregulated levels of CCL3 and CCL20 and increased recruitment of CD1a+ dendritic cells (DCs) in tumor infiltrations." (PMID 36551790, 2022). "Paradoxically, high circulating levels of IL-37 have been shown to associated with decreased survival in patients with metastatic epithelial ovarian cancer, possibly due to a unique tumour microenvironment in this form of cancer." (PMID 36483045, 2022). "Specifically, for LUAD, a study on patients’ samples showed that the loss of or reduced IL-37 expression in the tumor correlates with metastasis development." (PMID 36551790, 2022). "IL-37 is correlated with tumor size and is linked to disease-free survival and quantity by inducing tumor-infiltrating CD571 natural killer cells." (PMID 35955885, 2022). "In the present study, our data showed that IL-37 expression was markedly associated with tumor progression and chemo-resistance in vitro and in vivo." (PMID 32226541, 2020). "What is the mechanism underlying the inhibition of tumor progression and sensitization efficacy of Gem by IL-37?" (PMID 32226541, 2020). "Consistent with a role in tumor growth and metastasis, high levels of IL-37 in the serum of patients with ovarian cancer was associated with poor prognosis, poor overall survival and the progression-free survival." (PMID 31231372, 2019). "Of the five known splice variants of IL-37, tumor (cell and tissue) levels of IL-37b isoform were consistently elevated and demonstrated an appreciable positive prognostic potential with disease progression in cancer patients." (PMID 29641433, 2018). "Further tumor-limiting roles have been linked to IL-37 in renal carcinoma and non-small cell lung carcinoma." (PMID 29641433, 2018). "This study showed that patients with high expression level of IL-37 in HCC tumor tissue had better overall survival and disease-free survival, and the low expression of IL-37 in tumor tissue was an independent risk factor for poor prognosis." (PMID 29805973, 2018). "High expression of IL-37 in HCC tumor tissues was associated with better overall survival (OS) and disease-free survival (DFS)." (PMID 27835881, 2016). "IL-37 expression in NSCLC tissues is closely associated with the progression of the tumor." (PMID 41293155, 2025). "In the previous study, found that IL‐37 also played a role of anti‐inflammatory, inhibiting related inflammatory cells, including monocytes and monocyte‐derived DCs (MoDCs); however, tumor progression was also related to the loss of normal immune regulation processes." (PMID 36891351, 2023). "Furthermore, HCC overexpression of IL-37 is associated with increased recruitment of CD11c+ DCs in the tumor infiltration and suppression of the growth of the tumors." (PMID 37298214, 2023). "Finally, colonic IL-37 and tumor associated neutrophils (TAN) seem to be independent biomarkers of prognostic value, whereas colonic IL-38 seems to be a reliable and independent biomarker in predicting the 5-year survival post-surgery in CRC." (PMID 35186997, 2022).
tumor (continued). "IL-37 levels were found to be correlated with tumor development, stage, grade, and the improved overall survival of patients, and mutations and gene expression levels were associated with the differential distribution of immune cells infiltrating the tumor." (PMID 36551790, 2022). "Furthermore, in HCC tumor infiltration high prevalence of IL-37+CD1a+ DCs biopsies was linked to higher survival rates of patients." (PMID 36551790, 2022). "This is important since HCC clinical specimens have shown that decreased expression of IL-37 is negatively correlated with tumor size and positively associated with better overall survival and disease-free survival via the induction of tumor-infiltrating CD571 natural killer cells." (PMID 32582865, 2020). "Whether this variant of IL-37 is important in suppressing tumor growth and metastasis in all forms of cancer is unknown." (PMID 31231372, 2019). "In order to determine whether human IL-37 expression in IL-10KO mice is associated with a tumor protective immune status in the gut, we analyzed the levels of selected mRNA's linked to tumor formation." (PMID 31781119, 2019). "Collectively, these results validated that inflammation is required for tumor metastasis, and that IL-37 could effectively inhibit tumor metastasis by suppressing the tumor-associated inflammatory response." (PMID 28415700, 2017). "Since inflammation has now been confirmed as the seventh hallmark of tumours, many speculate that the anti-inflammatory cytokine IL-37 might influence inflammation-related tumours." (PMID 27225603, 2016). "Similarly, IL-37 was found negatively associated with OSCC tumour metastasis and cell motility in the present study." (PMID 27225603, 2016). "The role of IL-37 in cancer is complex and depends on the biological context, tumor type, immunosuppression, and inflammation status." (PMID 41596472, 2026). "IL-37/IL-38 can inhibit the pro-tumor activity of infiltrating MCs and macrophages by reducing angiogenesis and inflammation and inhibiting the cancerous microenvironment." (PMID 41596472, 2026). "Interleukin-37 (IL-37), an anti-inflammatory cytokine with reported tumour-suppressive properties, has emerged as a candidate biomarker in hepatocarcinogenesis." (PMID 42073372, 2026). "IL-37 can favor tumor activity by inducing immune tolerance, whereas it can counteract tumor development and growth by suppressing inflammation." (PMID 41596472, 2026). "IL-37 transgenic mice (IL-37tg) show a reduction in pro-inflammatory cytokines and inhibition of tumor growth and metastasis." (PMID 41596472, 2026). "This review explores IL-37's diverse effects on fundamental hallmarks of cancer, such as tumor cell proliferation, invasion, metastasis, and interactions with the immune system." (PMID 42238575, 2026). "IL-37 can be a friend in cancer by reducing tumor inflammation and suppressing NF-κB and MAPK pathways." (PMID 41596472, 2026). "While IL-37 demonstrates a protective role, suppressing tumour growth and promoting favourable immune responses, IL-38 appears to play a detrimental role, enhancing inflammation and immune evasion." (PMID 40191189, 2025). "In terms of immune regulation, IL-37 enhances anti-tumor immune responses by suppressing the chemotactic nature of Tregs." (PMID 41293155, 2025). "IL-37 is critical for ovarian tumor cells to stimulate MSCs to express pro-tumor cytokines and pro-angiogenic factors." (PMID 40676710, 2025). "In NSCLC, tumor cells transfected with IL-37 show reduced CD34 expression and decreased microvessel density." (PMID 41293155, 2025). "On the other hand, IL-37 has also been shown to have an inhibitory effect on angiogenesis, especially in the context of tumor treatment." (PMID 41293155, 2025). "Tumors frequently evade immune surveillance by elevating the local Treg population, and IL-37 can attenuate the accumulation of Tregs within the tumor microenvironment, thereby weakening their protective shield for cancer cells." (PMID 41293155, 2025).
tumor (continued). "In recent years, numerous studies have highlighted the significant role of IL37 in various types of tumours." (PMID 39500733, 2024). "In summary, the elevated expression of IL37 in OSCC tissues appears to be a response by tumour cells to counteract the inflammation induced by the hypoxic tumour microenvironment." (PMID 39500733, 2024). "Possible anti-tumor mechanisms of IL-37 include inhibition of both angiogenesis and tumor-promoting inflammation, and promotion of anti-tumor immunity." (PMID 39206201, 2024). "It is understandable that there are ethical challenges to obtaining gastric mucosa or hepatic tissue from HCC cohorts, but certainly the detection of IL-37 in GC tumor and adjacent normal gastric mucosa warrants further clarification." (PMID 39206201, 2024). "Interleukin 37 (IL37), a cytokine known for the ability to suppress inflammation and immunity, shows two seemingly contradictory functions in tumours." (PMID 39500733, 2024). "This suggests that IL37 indeed possesses a tumour‐promoting ability, which aligns with our own conclusions." (PMID 39500733, 2024). "To further confirm the mechanism, we demonstrated that pro‐IL37 was indeed secreted outside of tumour cells through GSDMD." (PMID 39500733, 2024). "IL37 promotes the proliferation of tumour cells, leads to the repolarization of M1 macrophage toward M2 macrophage, ultimately accelerating the progression of OSCC." (PMID 39500733, 2024). "The investigation into IL37 expression in tumour and normal oral mucosa of OSCC patients yielded significant findings." (PMID 39500733, 2024). "In an OSCC xenograft mouse model, the knockdown of IL37 resulted in a slower tumour growth rate, accompanied by an increase in the number of CD86+ M1 macrophages and a decrease in CD206+ M2 macrophages." (PMID 39500733, 2024). "In conclusion, the findings of this study suggest that the tumour inflammatory environment induced by hypoxia promotes IL37 expression via NLRP3 inflammasome activation, and IL37 release through NLRP3/GSDMD." (PMID 39500733, 2024). "Both IL37 mRNA and IL37 protein levels were found to be elevated in tumour tissues when compared to normal oral mucosa." (PMID 39500733, 2024). "This revealed that tumour-derived IL-37 promotes HUVEC apoptosis, inhibits migration, and impedes tubule formation in vitro." (PMID 38312834, 2024). "This shift led to an increased production of IL-12, TNF, and IL-1β, supporting the anti-tumour role of IL-37." (PMID 38312834, 2024). "In this study, we conducted an investigation into the expression levels of IL37 in OSCC tissues and observed a notable upregulation of IL37 in both tumour cells and the extracellular matrix." (PMID 39500733, 2024). "For investigating the specific role of IL37 in tumour associated macrophage (TAM) polarization, OSCC specimens were divided into three groups: weak group, moderate group and high group according to IL37 IHC score." (PMID 39500733, 2024). "IL37 was prominently expressed within the tumour cells and the extracellular matrix of tumour tissues." (PMID 39500733, 2024). "Consistently, IL-37 mRNA and protein expressions were significantly reduced in NSCLC tissues, and the descending protein was clearly associated with tumor state, TNM stage and shorter OS in patients." (PMID 37928545, 2023). "As an anti-inflammatory cytokine, IL-37 is proposed to activate anti-tumor immune response by suppressing pro-tumor inflammation that releases the immune suppression in the TME." (PMID 37928545, 2023). "In order to have a better understanding of the role of IL‐37 in promoting tumor immunity, we evaluated the immune cells with antigen phagocytic composition of tumor‐bearing skin tissue and SDLN." (PMID 36891351, 2023). "Specifically, by affecting the SIGIRR‐AMPK‐Akt signaling axis, which is related to the regulation of glycolysis in CD103+DCs, IL‐37 inhibited their anti‐tumor function." (PMID 36891351, 2023).
tumor (continued). "Certain researches stated that the expression of IL-37 protein in HCC tumor tissues was decreased and negatively correlated with tumor size, while its content in surrounding healthy liver tissues was proximity to normal." (PMID 37928545, 2023). "At the same time, to better understand the role of IL‐37 in anti‐tumor‐specific immunity, we established the B16‐OVA xenograft model in WT and IL‐37tg mice." (PMID 36891351, 2023). "Research has been shown to elaborate on the potential effects of IL-37 on tumor growth, immune responses, and tumor angiogenesis." (PMID 36874133, 2023). "As a matter of fact, there is hope for the use of IL-37 in a large variety of other conditions, including autoimmune, neurological, cardiovascular, and neoplastic diseases, to name but a few." (PMID 38067193, 2023). "In this review, we summarize the immunoregulation roles and mechanisms of IL-37 in anti-tumor process, and discuss its progress so far and potential as tumor immunotherapy." (PMID 37928545, 2023). "IL-37 expression levels were also found to correlate with the nodal metastasis status of the tumor, with the highest values detected in N3 biopsies; however, the group included a relatively small number of samples (n = 8, 0.26 (0.095))." (PMID 37298214, 2023). "Bioinformatics analysis revealed that IL-37 levels correlate with BLCA tumor development and are higher in patients with longer overall survival." (PMID 37298214, 2023). "Interleukin 37 (IL‐37), a member of the IL‐1 family, is considered a suppressor of innate and adaptive immunity and, hence is a regulator of tumor immunity." (PMID 36891351, 2023). "The study also confirmed that CD34 protein levels were reduced in IL-37-overexpressing NSCLC tumor tissues, implying a decrease in microvessel density (MVD)." (PMID 37928545, 2023). "Emerging data from clinical and preclinical studies strongly indicate the important contribution of IL-37 to anti-tumor immunity via control of the function of critical regulators in the TME." (PMID 37298214, 2023). "Altogether, these results suggested a pivotal role for IL-37 in promoting tumor progression in the CAC." (PMID 35046386, 2022). "In conclusion, these results demonstrated the role of IL-37 in driving pro-tumor immunity by cytotoxic T cell dysfunction." (PMID 35046386, 2022). "Possible anti-tumour mechanisms of IL-37 include inhibition of both angiogenesis and tumour-promoting inflammation, and promotion of anti-tumour immunity." (PMID 36483045, 2022). "It is also noteworthy that, overall, all human tumor biopsies express lower IL-37 compared to SIGIRR mRNA levels (1.029 ± 11.68 vs. 13.04 ± 8.911, respectively, n = 7932, p < 0.0001)." (PMID 36551790, 2022). "Additional in vivo experiments showed that overexpression of IL-37 in HCC cells resulted in increased recruitment of CD11c+ DCs in the tumor microenvironment and tumor growth delay." (PMID 36551790, 2022). "The functional mechanism of the novel IL-1 family member IL-37 in the tumor microenvironment is still unclear." (PMID 35046386, 2022). "Evidence of the role of IL-37 in cancer, emerging during the last years, support its tumor-protective properties exerted through the enhancement of anti-tumor immunity, specifically within the tumor microenvironment (TME)." (PMID 36551790, 2022). "Apart from immune-related effects, IL-37 also exerts its anti-cancer activity on other aspects of tumor development." (PMID 36551790, 2022). "Second, it suppresses migration through the inhibition of Rac1 activation in various tumor cell types; indeed, intracellular IL-37 binds to the C-terminal region of the protein, preventing its membrane translocation and downstream signaling." (PMID 36551790, 2022).